LEP (leptin)
Diseases named in the same sentence as LEP in open-access papers (continued):
Sharing a sentence is not in itself a finding about the gene and the disease.
Obesity (continued). "Furthermore, animal models of obesity have established that fatty acid mediated alterations in TLR2 and TLR4 signaling play a central role in the establishment of insulin and leptin resistance." (PMID 30131724, 2018). "Leptin, a 16 kDa polypeptide that is primarily released from white adipose tissue (WAT), is an important hormone for weight management via the homeostatic control of energy equilibrium, thus facilitating the prevention of obesity." (PMID 29874843, 2018). "When stratified by obesity status, biomarkers were associated with development of CKD and RKFD in non-obese, particularly for leptin and adiponectin." (PMID 30236068, 2018). "The likely reason for this is pronounced hyperphagia in both models that is predominantly driven by the lack of leptin signaling, and the resulting massive obesity that drives the development of insulin resistance and diabetes." (PMID 29483571, 2018). "Neither overweight/obesity nor gestational weight gain appear to be independent determinants of increased birth weight, insulin and leptin." (PMID 29925339, 2018). "Indeed, ER stress has emerged as a critical link in the development of leptin and insulin resistance in neurons of animals with HFD-induced obesity." (PMID 29457782, 2018). "A study aimed at exploring the relationship between obesity and depression found that, a combination of diet induced obesity and chronic unpredictable mild stress (CUMS) resulted in increased leptin levels but a decrease in LepR expression, along with depressive behaviors." (PMID 30405455, 2018). "PTPRJ expression in the hypothalamus was up-regulated by diet-induced obesity or a leptin treatment, and, thus, diet-induced leptin resistance did not occur in Ptprj-KO mice." (PMID 28912580, 2017). "Saturable transporter carries leptin across the BBB and defective transport may lead receptor errors and deteriorates with the increasing obesity." (PMID 28881823, 2017). "Likewise, mice overexpressing a constitutively active version of STAT3 in POMC neurons show elevated SOCS3 expression and develop obesity as a result of hyperphagia and decreased POMC expression accompanied by central leptin resistance." (PMID 28270795, 2017). "It appears that leptin has neuroprotective role, but in antipsychotic-induced leptin resistance and in obesity these neuroprotective properties are not so obvious." (PMID 29163240, 2017). "Relationships between leptin levels and lipid profiles may differ according to the pathological conditions of the patient, such as GBM, obesity, and hyperlipidemia." (PMID 29088261, 2017). "The main objective of this cross-sectional study was to evaluate the levels of leptin and adiponectin in patients with fibromyalgia with and without overweight/obesity." (PMID 28226002, 2017). "The aim of this study was to evaluate the levels of the adipokines leptin and adiponectin in patients with fibromyalgia with and without overweight/obesity." (PMID 28226002, 2017). "Our data are consistent with previous studies showing that B1R contributes to insulin resistance and obesity through a mechanism independent of leptin." (PMID 28824433, 2017). "The discrepancy between the two studies suggests that Zn supplementation-mediated cardiac protection from obesity and/or T2DM is likely dependent on leptin-mediated signaling, as shown by the impact of Zn on leptin levels; this will be further explored in future studies." (PMID 28272348, 2017). "There are no data showing a direct correlation between obesity and increased blood leptin levels with folliculoma." (PMID 28861689, 2017). "Saturated fatty acids, which are elevated in obesity, are able to bind and activate toll-like receptor 4 (TLR4) and inhibition of TLR4 or neuronal deletion of the TLR adaptor molecule MyD88 protects from HFD-induced leptin resistance and obesity." (PMID 28270795, 2017).
Obesity (continued). "The findings of this study demonstrated that patients with fibromyalgia and overweight/obesity had decreased leptin levels and that the levels did not correlate with clinical parameters associated with fibromyalgia." (PMID 28226002, 2017). "On the other hand, POMC-specific PTEN−/− mice develop leptin resistance and obesity, suggesting that chronic elevation of PIP3 in POMC neurons may interfere with hypothalamic leptin activity." (PMID 28270795, 2017). "Certain obesity-associated markers such as triglycerides (TG) or non-esterified fatty acids (NEFA) were increased in BCa patients compared to controls, while leptin or adiponectin were not significantly altered." (PMID 29113405, 2017). "These high‐fat diets (HFDs) also contribute to the development of obesity, which is often, but not always, associated with T2DM, and can lead to both insulin and leptin resistance." (PMID 28638713, 2017). "Other authors reported similar results in children, suggesting a role of leptin as a potential modulator of glucose metabolism and insulin resistance, regardless of obesity." (PMID 27598976, 2017). "Unlike with leptin or insulin, conditions such as those in oxytocin resistance are not present in obesity." (PMID 28819236, 2017). "Though the link between obesity and breast cancer has not been exactly delineated, elevated leptin levels have been identified as one of the key factors for breast cancer development, progression and metastasis." (PMID 28930270, 2017). "MLD incorporated with dietary restriction and exercise treatment exhibit effects in alleviating high-fat diet-induced obesity, hyperglycemia, hyperlipidemia, hypertension, hepatic injury and insulin resistance, which are possibly due to the down-regulation of TNF-α, leptin and PKB." (PMID 28241808, 2017). "In the congenital leptin deficiency, the lack of this hormone generates hyperphagia and massive obesity, which is reversed following peripheral administration of recombinant human leptin." (PMID 28626772, 2017). "Although obesity alone is not linked with decreases in bone mass, obese individuals with T2DM often exhibit leptin resistance that likely plays a role in increased incidence of fractures." (PMID 28183304, 2017). "Practically this should demonstrate that the leptin gene is not a candidate for routine genetic screening in obese patients, but it will probably be included in multigene panels for monogenic obesity." (PMID 29101506, 2017). "The administration of human recombinant leptin to these patients does not seem to reduce intake or body fat, indicating a resistance to leptin action in multifactorial obesity." (PMID 28626772, 2017). "Obesity-derived LPA, leptin, and PAI-1 are all known as a promoter of BC progression." (PMID 28186980, 2017). "The BTBR ob/ob mouse model has been described as a model of advanced obesity-related diabetes due to a lack of the hormone leptin." (PMID 28281693, 2017). "Other authors reported similar results in studies of prepubertal children with normal and excess weight, suggesting a role of leptin as a potential modulator of glucose metabolism and insulin resistance, regardless of obesity." (PMID 27598976, 2017). "Our results suggest that the changes observed in the brain pathways activated by resistin and leptin can be observed without overt obesity." (PMID 29234283, 2017). "DIO mice develop peripheral leptin resistance primarily due to obesity, with no genetic functional defect in leptin or its receptor." (PMID 28640857, 2017). "These isoforms activate JAK2, but not STAT3 signaling, and, as such, are not involved in the anti-obesity effects of leptin." (PMID 27375555, 2016). "Furthermore, previous studies demonstrated that SOCS3 and PTP1B levels were elevated in a mouse model of obesity, suggesting the involvement of SOCS3 and PTP1B in leptin resistance with obesity." (PMID 27375555, 2016).
Obesity (continued). "Data also revealed that these mice have reduced leptin sensitivity and LRb signal transduction in a manner independent of obesity." (PMID 26926121, 2016). "Abnormal level of leptin and dysregulation of leptin signaling have been identified to be crucial players in pathogenesis of HCC, contributing to the malignant development and progress of obesity-related liver cancer." (PMID 26982332, 2016). "Postpartum the mean leptin concentrations were higher with increasing obesity category, although not reaching statistically significant difference between women in obesity class II and III." (PMID 27257506, 2016). "Although the placenta is a source of plasma leptin, which can be stimulated by obesity and GDM, we did not observe differences in leptin gene expression, suggesting that adipocytes, rather than the placenta, are the main origin of differences in plasma leptin." (PMID 26513002, 2016). "Instead, we demonstrate that silencing BBS proteins, but not IFT88, impair the trafficking of the LRb to the plasma membrane leading to central leptin resistance in a manner independent of obesity." (PMID 26926121, 2016). "Our results suggest that neither increased glucocorticoid, insulin, and leptin levels, nor decreased adiponectin levels in fathers are sufficient to confer soma-to-germline information transfer in EI of obesity via the paternal lineage." (PMID 26662513, 2016). "Whereas activation of CB1R by eCBs promotes appetite via a leptin-regulated hypothalamic neural appetitive circuitry, its chronic blockade by globally acting CB1R antagonists inhibits food intake both in rodents and individuals with obesity." (PMID 27900261, 2016). "In line with this defective leptin responsiveness, partial inactivation of PI3K-C2α led to the development of adult-onset obesity, with accompanying hypertrophy of the adipose tissue, abnormal hepatic lipid accumulation, glucose intolerance, hyperinsulinaemia and insulin resistance." (PMID 27138914, 2016). "In the present study leptin was positively associated and SOCS-3 was negatively associated with MMP levels in SF in obese but not in non-obese patients with OA, further confirming the importance of the leptin-SOCS-3 axis in cartilage metabolism and its possible significance in obesity-induced OA." (PMID 27716333, 2016). "It is also known that high leptin sensitivity keeps animals thin and leptin resistance/lack of leptin leads to obesity." (PMID 26955508, 2016). "In obesity, a putative resistance to leptin develops, which prevents the normal negative feedback control mechanism responsible for adipocyte leptin production from functioning properly." (PMID 26942201, 2016). "We demonstrated that KBH-1, as an herbal composition of Polygala tenuifolia, Curcuma longa, and Saururus chinensis extracts, improved hepatic steatosis and leptin resistance in a HFD-induced obesity model through the increase of AMPK phosphorylation and the up-regulation of leptin-mediated signals." (PMID 27618865, 2016). "In the absence of functioning leptin, the ob/ob mouse rapidly develops obesity and hyperglycemic conditions similar to T2DM." (PMID 27055280, 2016). "This complex relationship between obesity and BMD could be explained by the effect on bone of a series of adipokines and cytokines secreted by adipose tissue, such as leptin, resistin, adiponectin, interleukin 6, and tumor necrosis factor-alpha." (PMID 27809297, 2016). "Leptin has been identified as an important protein involved in the weight regulation system, and the absence of leptin leads to increased appetite and decreased energy expenditure and subsequently obesity." (PMID 27189377, 2016).
Obesity (continued). "Previous studies have explored the association between ELC and obesity or MS but data on the associations between ELC and other adiposity markers such as leptin, adiponectin and uric acid are lacking." (PMID 26790748, 2016). "This phenomenon of leptin concentration underestimating body fat stores is similar to that seen in rodent models of obesity whereby formerly obese rats that lose weight do not have restored leptin concentrations after weight regain." (PMID 26937246, 2016). "Briefly, obesity exposed neonates had higher UCB leptin levels compared to not exposed neonates and a trend for increased levels in gestational diabetes exposed neonates." (PMID 27440187, 2016). "Here we evaluated the effect of high maternal leptin, in the absence of maternal hyperglycemia or obesity, on offspring cardiovascular health, with specific emphasis on blood pressure and resistance artery function and structure." (PMID 27187080, 2016). "Four studies reported similar levels of IL-6 and five studies reported similar levels of adiponectin between obese and nonobese individuals with CP, whereas 3 studies reported comparable levels of GCF leptin among CP patients with and without obesity." (PMID 27795608, 2016). "Collectively, these data demonstrate that leptin resistance in mice lacking the Bbs1 gene in the LRb-expressing cells is not secondary to obesity." (PMID 26926121, 2016). "SOCS3 also exerts its negative effect on muscle by sequestering leptin, leading to the leptin resistance in skeletal muscle observed in obesity." (PMID 27746742, 2016). "Mc4r-null mice feature hyperphagic obesity without pathologically suppressed leptin levels, suggesting that they have the potential to model the extended spectrum of NAFLD more faithfully than ob/ob mice." (PMID 27899914, 2016). "Presently, there is lack of observational studies assessing leptin in relation to cancer while accounting for inflammation and different definitions of obesity." (PMID 26632325, 2016). "PNE does not result in obesity and type 2 diabetes but instead enhances leptin-melanocortinergic feeding and body weight regulation via POMC neurons in adult offspring." (PMID 27609221, 2016). "We examined leptin and its ratio to adiponectin, in asthmatics and nonasthmatics, with and without obesity." (PMID 26770217, 2015). "In this study, leptin and adiponectin levels in both lung homogenates and blood sera were not noticeably different between the obese and obesity-treated mice." (PMID 25658739, 2015). "The absence of hypertrophic adipose tissue at 3 months in both Bbs10−/− and Bbs12−/− mice does not support the classical leptin resistance theory leading to obesity in the BBS." (PMID 26273430, 2015). "In conclusion and within the limits of this study, it was not possible to establish a positive link between CP and obesity in terms of differences in the levels of adiponectin, leptin and TNF-α between obese and NW subjects with and without periodontitis." (PMID 26330934, 2015). "Leptin and leptin-signaling pathway have emerged as leading targets for disrupting obesity-breast cancer link; therefore, developing effective, non-endocrine, non-toxic agents for the inhibition of neoplastic effects of leptin is highly important." (PMID 26359358, 2015). "Altogether these results suggest that LEP and ADIPOQ DNA methylation profiles might be involved in the pathology of obesity and cardiometabolic diseases." (PMID 25929254, 2015). "Although circulating levels of leptin rise in obesity, these individuals are thought to be leptin resistant due to lack of satiation." (PMID 26379553, 2015). "In summary, we conclude that serum irisin levels seems in light of our present results not affected by obesity, nutritional status, or leptin in rodents." (PMID 26568663, 2015). "Nevertheless, LEP and ADIPOQ epigenetic profiles in adipose tissue and their associations with obesity and obesity-associated metabolic perturbations have not been assessed so far." (PMID 25929254, 2015).
Obesity (continued). "Lepob/ob mice lacking GluN2B in AgRP neurons are also more sensitive to leptin's anti-obesity actions." (PMID 26500840, 2015). "Evaluation of leptin treatment in the absence of obesity provides clinically relevant data due to the lack of leptin resistance as a confounder." (PMID 25797953, 2015). "Circulating levels of leptin increase during obesity but transport into the brain does not increase proportionally, with the transport system becoming saturated." (PMID 25859240, 2015). "Male mice lacking AR develop insulin resistance, leptin resistance, and late onset obesity primarily due to decrease in locomotor activity, a component of energy expenditure." (PMID 26491443, 2015). "While these findings indicate an important interaction between AT1-aa and the ET-1 system in the response to placental ischemia, the effect of obesity or obesity-related metabolic factors such as leptin on AT1-aa-induced ET-1 production has not been examined." (PMID 26569331, 2015). "In obesity the expression of the leptin gene and its circulating concentration are elevated without any regulatory effects on body weight, with the development of resistance." (PMID 25871295, 2015). "Given that leptin and leptin-signaling pathway are prime targets for disrupting obesity-breast cancer link, developing effective, non-endocrine, non-toxic agents for prevention of the neoplastic effects of leptin are highly important." (PMID 26036628, 2015). "However, despite a vast body of research, the role of LEP and ADPN in the pathogenesis of obesity and cardiovascular diseases still raises a lot of controversies, for example due to discrepancies between clinical and animal research findings." (PMID 26389928, 2015). "The results obtained in this study also have not found any correlation between obesity and metabolic disorders in different genotypes of the leptin genes." (PMID 26504811, 2015). "In obese ob/ob mice, in which a defect in the leptin gene results in hyperphagia and subsequent obesity, genetic ablation of GIPR improved not only obesity by increasing energy expenditure, but also insulin insensitivity and glucose tolerance without seriously affecting insulin secretion." (PMID 26075286, 2015). "Because the correlations between LEP DNA methylation levels and BMI were attenuated after adjusting for CRP levels, we hypothesized that the obesity-related proinflammatory response per se contributed to the alteration of LEP epigenetic profile in blood cells." (PMID 25929254, 2015). "Our results suggest that leptin is a marker of obesity rather than of adipocyte differentiation, since obese ex vivo isolated adipocytes but not differentiated 3T3-L1 adipocytes were the main producers of leptin in the system." (PMID 25599228, 2015). "Accordingly, we hypothesized that decreased LEP DNA methylation and increased ADIPOQ DNA methylation in adipose tissue could lead to higher degree of obesity and pro-inflammatory state, dyslipidemia, hypertension and insulin resistance." (PMID 25929254, 2015). "Given the importance of leptin in driving obesity-breast cancer axis and the current lack of effective, clinically viable leptin-antagonists, it is imperative to develop novel leptin-antagonists that can potentially be utilized for clinical use." (PMID 26036628, 2015). "Levels of leptin in humans are log-linearly increased in relation to obesity and lack of leptin induces severe obesity, demonstrating that leptin signaling is necessary for normal feedback control of body weight." (PMID 25994184, 2015). "We have thus hypothesized that LEP and ADIPOQ DNA methylation changes might be involved in obesity development and its related complications." (PMID 25929254, 2015). "Only metabolically healthy obese women had a lower leptin and higher adiponectin level as opposed to women with complicated obesity." (PMID 26504811, 2015).